AIMP1 (aminoacyl tRNA synthetase complex interacting multifunctional protein 1)
Diseases named in the same sentence as AIMP1 in open-access papers (continued):
Sharing a sentence is not in itself a finding about the gene and the disease.
tumor (34 papers, 2006 to 2025). "In our eight mRNAsi based signature, high expression of RGS16, LYVE1, hnRNPC, ANP32A, and AIMP1 are correlated with a high risk of death as these genes focus in promoting cell proliferation and tumor progression, similar to stem cells." (PMID 33329703, 2020). "Based upon this observation, we sought to expand further upon the relationship between tumor-associated AIMp1 and good outcomes in cancer." (PMID 29379495, 2017). "Collectively, these findings indicate that AIMP1 actively participates in tumor immunity through regulating various physiological processes, such as Th1 polarization, NK cell activity, and MDSC functions." (PMID 32709848, 2020). "Meanwhile, The Cancer Genome Atlas (TCGA) database analysis showed that the expression of AIMP1 in nearly 9000 primary tumor samples was highly correlated with long-term survival." (PMID 32709848, 2020). "In this prognostic signatures, high expression of RGS16, LYVE1, hnRNPC, ANP32A, and AIMP1 focus in promoting cell proliferation and tumor progression." (PMID 33329703, 2020). "Cohorts of WT and AIMp1−/− mice were inoculated subcutaneously (s.c.)with 200,000 tumor cells and subsequently vaccinated with BMDC loaded with recombinant OVA protein and its immunodominant MHC class I peptide epitope SIINFEKL." (PMID 29379495, 2017). "In vivo, recombinant human AIMp1 can inhibit the growth of multiple tumor cell lines or transplanted tumors, possibly by upregulation of tumor necrosis factor receptor and also through negative regulation of the immunosuppressive microenvironment." (PMID 29379495, 2017). "The data indicated that AIMp1 presence within the BMDC vaccine promotes type 1 polarization of tumor infiltrating lymphocytes in vivo." (PMID 29379495, 2017). "While prospective genetic studies will be needed to understand the source of AIMp1 expression within the tumor tissues, the results serve to expand the understanding of AIMp1 functionality from in vitro experiments and animal models to human study." (PMID 29379495, 2017). "Particularly, AIMP1 plays an important regulatory role in tumor immunity." (PMID 32709848, 2020). "Additionally, aminoacyl-tRNA synthetase-interacting multifunctional protein 1 (AIMP1), a novel pleiotropic cytokine, was shown to inhibit the expansion of MDSCs and tumor growth by reducing the MDSCs in tumor tissues." (PMID 32443699, 2020). "The cells exhibiting an active cell cycle progression were reduced in tumor tissues of AIMP1-treated mice, and the blood levels of TNF-α and IL-1β were increased, indicating that AIMP1 might play an anti-tumor role by inducing tumor inhibiting cytokines." (PMID 32709848, 2020). "We also demonstrated that AIMP1 expression could be correlated with the immune signatures of activated tumor-infiltrating DC and TH1 T-cell subsets." (PMID 29379495, 2017). "Cancer patients with AIMp1 expression levels in the highest tertiles exhibited a 70% survival advantage at 15-year postdiagnosis as determined by bioinformatics analysis of nearly 9,000 primary human tumor samples in The Cancer Genome Atlas database." (PMID 29379495, 2017). "Given this important observation and the clear association of AIMp1 with TH1 immune processes, we analyzed the relationship between AIMP1 expression and patient outcome among the nearly 9,000 primary tumor samples in the pan-cancer TCGA database that could be linked to outcomes data." (PMID 29379495, 2017). "First, we investigated the mRNA expression levels of AIMP1/2/3 in TCGA-GBM (n = 163), TCGA-LGG (n = 512) and normal brain (GTex, n = 207) in order to determine possible differential mRNA expression in the tumor tissue compared with normal brain tissue." (PMID 40874786, 2025). "Our data indicated downregulation of the connective protein AIMP1, QARS and KARS, while MARS and EPRS were found upregulated in tumor specimens." (PMID 33092114, 2020).
tumor (continued). "To investigate if the antitumor effect of AIMp1 relied upon activation of certain immune cell subsets (i.e., DC), we took advantage of the well-characterized B16-OVA tumor cell line which expresses the model antigen ovalbumin (OVA)." (PMID 29379495, 2017). "Administration of WT BMDC vaccines upregulated the infiltration of IFN-γ+ T-cells and NK cells within the tumor, whereas infiltration of IFN-γ+ cells among animals vaccinated with AIMp1−/− BMDC was identical to that of unvaccinated mice." (PMID 29379495, 2017). "In contrast, tumor growth was poorly controlled in both WT and AIMp1−/− cohorts vaccinated with AIMp1−/− BMDC, ultimately reaching comparable size as non-vaccinated controls with only a short delay." (PMID 29379495, 2017). "This can potentially indicate any role AIMP1/2/3 may play in tumor aggressiveness and progression in general, regardless of treatment." (PMID 40874786, 2025).
cancer (18 papers, 2006 to 2025). A tumor composed of atypical neoplastic, often pleomorphic cells that invade other tissues. "Among the components of ARSN, in our two results, both GARS and AIMP1 showed relatively higher cancer-associated network, indicating their potential importance in cancer biology." (PMID 22952576, 2012). "Based on the previous, downregulation of QARS and AIMP1 could lead to inhibition of apoptosis, which is a hallmark of cancer." (PMID 33092114, 2020). "To examine the potential association of ARS family with cancer at a systemic level, we compared the expression profiles of the genes encoding the 20 human cytoplasmic ARSs and AIMP1–3 (AIMPs) with those of known DTGs obtained from the US National Cancer Institute’s cancer gene index (CGI)." (PMID 22952576, 2012). "AIMP1/2/3 expressions correlated significantly with angiogenesis across The Cancer Genome Atlas cancers." (PMID 40874786, 2025). "Strikingly, AIMP1 expression showed significant positive correlation across all cancers except CHOL." (PMID 40874786, 2025). "The 8-mRNAsi based prognostic model in our signatures includes RGS16, LYVE1, hnRNPC, ANP32A, AIMP1, ZNF66, PIK3R3, and MAP2K7, in which several genes have been reported to be linked with stemness features or be involved in cancer progression." (PMID 33329703, 2020). "More recently, AIMp1 was reported to be secreted by cancer cells under conditions of stress in a manner substantially different from that of EMAPII." (PMID 29379495, 2017). "Among the components of ARSN, relatively higher cancer-associated network was shown by GARS, MARS, WARS, RARS, CARS, AIMP1 (SCYE1) and AIMP3 (EEF1E1) (green nodes)." (PMID 22952576, 2012). "To establish possible associations between AIMPs and angiogenesis in cancer, we investigated the correlation between AIMP1/2/3 and the angiogenesis Panther pathway and Kyoto Encyclopedia of Genes and Genomes pathway gene sets mRNA expressions across 33 TCGA cancers." (PMID 40874786, 2025). "Strikingly, RARS overexpression significantly reduced AIMP1 secretion in HeLa and MCF7 cells, indicating that RARS might participate in tumorigenesis by regulating the secretion of AIMP1 in cancer cells." (PMID 33330488, 2020). "However, for the sum total of all tumors, the data indicated that primary tumor AIMp1 expression was at least as important as that of IFN-γ to long-term survival in cancer." (PMID 29379495, 2017). "Also, AIMP1, MARS, and RARS have relatively higher association with cancers, indicating their potential importance in cancer biology and the needs of pathological mechanistic studies." (PMID 22952576, 2012). "The cell type-specific role of AIMp1 in TH1 immunity remains poorly understood, and we are the first to investigate its function within DCs in the context of host immunity against cancer and intracellular infection." (PMID 29379495, 2017). "Here, we not only summarize the biological functions of AIMP1, EMAP II, AIMP2, AIMP2-DX2, and AIMP3, but also focus on their emerging roles in regulating tumorigenesis, suggesting that their thorough study may provide new insights into cancer treatment." (PMID 32709848, 2020). "While there has been progress in understanding the role of AIMP1 in cancer, GARS functions in cancer biology have not been defined." (PMID 22952576, 2012).
infection (2 papers, 2017 to 2022). The state of being infected such as from the introduction of a foreign agent such as serum, vaccine, antigenic substance or organism. "Neutrophils that respond quickly to infection infiltrated the lung at a significantly lower level in AIMp1−/− animals at day 7 postinfection." (PMID 29379495, 2017). "The lack of effective innate and adaptive antiviral immunity observed among AIMp1−/− mice following sublethal infection may be responsible for the higher mortality observed among these animals following fully lethal doses." (PMID 29379495, 2017). "Despite no overt clinical phenotype at the earliest stages of infection amongst the AIMp1−/− survivors, AIMp1 deficiency mediated significant effects on innate and adaptive immune responses on days 7 and 15 postinfection." (PMID 29379495, 2017).
neurological diseases (2 papers, 2020). "HLD3-associated AIMP1 mutations are actually associated with severe neurological disorders in which neuronal cells are strongly damaged." (PMID 32384815, 2020). "Pathogenic mutations in AIMP1 have been reported to be associated with neurological diseases, such as neurodegenerative disease, pontocerebellar hypoplasia, and intellectual disability." (PMID 32709848, 2020).
neurodegenerative disease (1 paper, 2025). A disorder of the central nervous system characterized by gradual and progressive loss of neural tissue and neurologic function. "Previous research has demonstrated that AIMP1 was involved in neurodegenerative disease, including AD." (PMID 40522094, 2025). "In the present study, we revealed a significant upregulation of AIMP1 levels in the blood of PD patients, consistent with previous observations in other neurodegenerative diseases." (PMID 40522094, 2025).
AIMP1 also shares sentences with these, for which no sentence is quoted: pancreatic cancer (6 papers); emphysema (4); bronchopulmonary dysplasia (3); lung disease (2); lymphoma (2); adenocarcinoma (1); astrocytoma (1); Autoimmunity (1); brain tumor (1); chronic obstructive lung disease (1); colon cancer (1); cortical cerebral atrophy (1); COVID-19 (1); dementia (1); hepatocellular carcinoma (1); Hepatomegaly (1); infectious disease (1); liver fibrosis (1); lymph node metastasis (1); Lymphatic Metastasis (1); lymphopenia (1); mantle cell lymphoma (1); metastatic tumors (1); microcephaly (1); myocardial infarction (1); myocardial ischemia (1); non-Hodgkin lymphoma (1); non-small cell lung carcinoma (1); obstructive lung disease (1); Ohtahara syndrome (1).
A further 12 diseases each share a sentence with AIMP1 in 1 paper.